TMEM69 (transmembrane protein 69)
Synonyms: C1orf154; FLJ21029
Tractability: Antibody: UniProt predicts a signal peptide or a membrane-spanning region.
Gene: Protein-coding gene on chromosome 1 (45,688,149 to 45,694,443, forward strand). Ensembl gene ENSG00000159596.
Subcellular location: Membrane
Subcellular location (Human Protein Atlas): Nucleoplasm
Gene Ontology:
Molecular function: protein binding
Cellular component: mitochondrion; membrane
Genetic constraint (gnomAD): Loss-of-function variants: 18 observed, 16.25 expected, observed/expected ratio (o/e) 1.11, 90% interval 0.76 to 1.63. The upper end of that interval is the gene's LOEUF score, 1.63, which puts it in group 6 of 6, group 1 being the genes least tolerant of losing a copy. Missense variants: 219 observed, 284.58 expected, observed/expected ratio (o/e) 0.77, 90% interval 0.69 to 0.86. Synonymous variants: 77 observed, 98.81 expected, observed/expected ratio (o/e) 0.78, 90% interval 0.65 to 0.94.
Homologues: Orthologues: chimpanzee TMEM69 (99% identical), macaque TMEM69 (89% identical), dog TMEM69 (78% identical), pig TMEM69 (74% identical), rabbit TMEM69 (74% identical), guinea pig TMEM69 (73% identical), mouse Tmem69 (68% identical), rat Tmem69 (68% identical), tropical clawed frog tmem69 (39% identical), zebrafish tmem69 (38% identical).
Diseases named in the same sentence as TMEM69 in open-access papers:
TMEM69 is named in the same sentence as 1 disease in open-access papers, as found by Europe PMC text mining. Sharing a sentence is not in itself a finding about the gene and the disease. The quoted sentences say what the papers report.
colon cancer (2 papers, 2006 to 2022). "Selection of some of the most suitable mRNAs (TMEM69, RANBP3 and PRSS22) that were assayed in blood samples from normal subjects and patients with colon cancer as possible markers for the presence of epithelial cells in the blood, using reverse transcription – polymerase chain reaction (RT-PCR)." (PMID 17054783, 2006).